CD163 (CD163 molecule)
Diseases named in the same sentence as CD163 in open-access papers (continued):
Sharing a sentence is not in itself a finding about the gene and the disease.
tumor (continued). "Another type of cells that has a role in promoting tumor development in cHL are tumor-associated macrophages (TAM), recognized by their expression of CD68 (M1 phenotype) and/or CD163 (M2 phenotype), which inhibit anti-tumor response, stimulate angiogenesis and migration of tumor cells." (PMID 35327381, 2022). "In patients that had not undergone neoadjuvant chemotherapy, high stromal CD163+ TAMs/M2 tumor-associated macrophages were associated with poor survival." (PMID 36139575, 2022). "Furthermore, RNA sequencing analysis from TCGA data showed that the expression of NOS3/NOS3 positively correlated with the expression of CSF1, CSF1R, CD163, and several other tumor-promoting immune cell markers in high-grade PCa (Gleason 9)." (PMID 36209194, 2022). "Many tumors are highly infiltrated by CD163+ M2c pro-tumorigenic macrophages which actively suppress anti-tumor immune responses by: upregulation of PD-L1, downregulation of CD80/86, and release immunosuppressive cytokines and metabolism-altering factors like IDO and NO13,34,35." (PMID 35379805, 2022). "This could also be readily observed through comparison of the number of cells that expressed the macrophage markers CD68, CD86, and CD163 in paired human tumor lesions and adjacent normal tissue in the same tissue block." (PMID 35326625, 2022). "The counts of CD163+ cells at the tumour area, but normally higher than that of CD86+ cells." (PMID 34964155, 2022). "Therefore, we proposed that malignant TCyEM cells appeared to produce high levels of CCL5 and CCL4 to recruit and polarize CD163-expressing M2 TAMs, forming a tumor-supporting environment in TCyEM cases." (PMID 35241665, 2022). "Previous research has produced contradictory results regarding prognostic significance of CD68+ and CD163+ tumour associated macrophages (TAMs), reporting both negative and positive prognostic effect." (PMID 36114487, 2022). "In this case, in which way do Tregs and CD163+ macrophages migrate to the tumor?" (PMID 36551693, 2022). "CD163 is commonly defined as a marker for tumor-supporting TAM phenotype." (PMID 36686729, 2022). "In addition to altered T cells, the ICC/IDC TME was associated with elevated macrophage expression of CD163 and MSR1, markers of pro-tumor M2 macrophages." (PMID 36229464, 2022). "Tumor-promoting TAMs tend to express M2-like macrophage markers, including CD163." (PMID 35053472, 2022). "CD163 and CD68 are factors linked with M2-polarized tumor-associated macrophages (TAMs)." (PMID 35454913, 2022). "According to the immunohistochemical results from our clinical samples, both CD163 and CD68 expression was positively correlated with VM enhancement, suggesting that the increased recruitment of TAMs was associated with VM enhancement in RCC tumor tissues." (PMID 35443741, 2022). "CD162 (PSGL-1) is a pro-atherogenic marker as it binds platelets, CD163 is a marker of tumor-supporting macrophages, CD169 defines tolerogenic (anti-inflammatory) monocytes binding to red cells, CD97 is an EGF-TM7 receptor, and pattern-recognition-receptor CD204 engagement is pro-inflammatory." (PMID 35159079, 2022). "Furthermore, the estimate scores and tumor purity indicate that there was a significant difference between the low and high CD163 expression groups, where a low expression of CD163 was related to higher tumor purity." (PMID 36551651, 2022). "As mentioned, patient 1 had an especially rapid tumor response which may be related to extremely high PD-L1 expression in the tumor and CD163 expression in the paracancerous stroma." (PMID 35095878, 2021). "Indeed, in our solid tumor-bearing humanized mouse model, tumor-infiltrating CD163+ TAM-like cells were successfully removed by treatment with H22-dPBD." (PMID 33692791, 2021). "Cells of innate immunity, mainly tumor-associated macrophages (TAMs) can be polarized into antitumoral M1 macrophages, expressing CD68, and protumoral and immunosuppressive M2 macrophages, characterized by coexpression of CD68 and CD163." (PMID 33494389, 2021).
tumor (continued). "Since ST11 K. pneumoniae might exert its tumor-promoting effects through activating CD163+ TAMs, we examined whether ST11 K. pneumoniae skewed M2 polarization of peritoneal macrophages." (PMID 34606408, 2021). "CD163+ TAMs seem to function as a contributor for tumor growth, metastasis, and poor prognosis." (PMID 33765961, 2021). "In tumor-adjacent tissues, lymphocytes expressed Spi-B, and alveolar macrophages expressed CD163." (PMID 34141615, 2021). "Three immune cell markers, the chemokine CC motif ligand 2 (CCL2), the pan macrophage marker CD68, and the M2 macrophage marker CD163, were examined using immunohistochemistry to determine their predictive value for chemotherapy responses in different nodal stage and tumor stage subgroups." (PMID 33467469, 2021). "Recent findings show that CD163+ macrophages promote tumor progression." (PMID 33763066, 2021). "Moreover, a study of EC patients who received neoadjuvant chemotherapy (NAC) followed by surgery demonstrated that high tumor CD163+ M2 macrophage infiltration is an independent predictor of response to NAC, and associated with poor prognosis and OS." (PMID 33995371, 2021). "However, this group of patients showed also an increased frequency of tumor cells within a 20 μm radius from CD163+ M2-polarized macrophages, and a higher percentage of CD8+ T lymphocytes within a 20 μm radius from CD163+ TAM." (PMID 33947438, 2021). "Some phenotypes that were co-expressing PD-L1, FKBP51s, and/or CD163 appeared to be correlated with the necrosis score, suggesting that changes in the tumor microenvironment of GBM could influence their development." (PMID 33917598, 2021). "CD68+/CD163+ TAMs were found to surround IR/IGF1R-stained PDAC tumor cells." (PMID 34638472, 2021). "The immunosuppressive cells promoting tumor growth are regulatory T (Treg) cells, myeloid-derived suppressor cells (MDSCs), CD163+ (M2-type) tumor-associated macrophages (TAM), N2-type tumor-associated neutrophils (TAN), tumor-associated mast cells, and immature dendritic cells." (PMID 35008368, 2021). "CD163 monocytes appeared to respond to the surgical removal of the tumor." (PMID 33917598, 2021). "Further investigation on the relationship between CD47 expression and CD163+ macrophages in tumor might assist to justify the efficacy of targeting CD47 therapeutic approach in PanNETs." (PMID 33765961, 2021). "Furthermore, the ratio of CD163-expressing M2-polarized TAMs in tumor nests was significantly higher in NE-low vs. NE-high tumors (70% vs. 31%)." (PMID 34200100, 2021). "The anti-inflammatory CD163+ macrophages (M2-like) were more prevalent in advanced tumor stage and exclusively located in invasive tumor front, whereas the CD80+ macrophages (M1-like) were predominant in less invasive tumors and predominantly distributed in tumor-adjacent normal mucosa." (PMID 33763066, 2021). "CD163+ cell numbers also differed significantly between grade 2 and grade 3 tumors, with the latter having increased myeloid cell infiltration in the Tumor, PT Tumor and IT Tumor compartments." (PMID 34194435, 2021). "In another study of the PROMIX trial, a decrease to low levels (<10%) of FOXP3+ T-lymphocytes in biopsies taken after cycle 2 of NAC was significantly associated with an improved DFS, whereas concentration changes of CD163 macrophages during NAC were unrelated to survival or tumor response." (PMID 34771604, 2021). "Importantly, in patients with residual tumor, most of the peripheral monocytes that in the preoperative stage were CD163/FKBP51s− had turned into CD163/FKBP51s+." (PMID 33917598, 2021). "Brentuximab vedotin kills CD30+ CD163+ TAMs and might suppress tumor formation in MF, suggesting that brentuximab vedotin might be suitable for combination with topical steroids or phototherapy." (PMID 33540765, 2021).
tumor (continued). "The presence of tumor-infiltrating immune cells, here represented as macrophages characterized by the markers CD68, CD163, and CCL2, was associated with a superior prognosis, and chemotherapy may not add an advantage for prognosis." (PMID 33467469, 2021). "In summary, our study demonstrated that CD86/CD163 ratio could effectively stratify stage II-III CRC into two different subgroups with a low and high risk of tumor recurrence and mortality." (PMID 34512652, 2021). "In addition, CD163+ macrophages were also present in the tumor vasculature itself as shown in BTCOE 4443 and in agreement with our previous data." (PMID 34572134, 2021). "CD163+ TEMs also preferentially infiltrate the tumor perivascular area." (PMID 35008355, 2021). "Combined with the phenomenon that M2 macrophage polarization could be induced by HO-1 overexpression, the correlation of HO-1 and CD163 might be involved in M2 TAMs activation and tumor aggressiveness in NPC." (PMID 33589574, 2021). "On the other hand, the bone marrow-derived macrophages that infiltrate the brain tissue showing M2-like (CD163+) polarity might promote tumorigenesis by creating an immunosuppressive tumor microenvironment (TME)." (PMID 34439274, 2021). "In addition, higher serum levels of the M2 marker CD163, and higher ratio of CD163+ cells to total macrophages correlate with a higher tumor grade, worse progression-free survival, and early relapse of serous OC after first-line chemotherapy." (PMID 34638494, 2021). "Moreover, CD163 has also been reported to bind TWEAK37 that has a downregulated expression in tumor tissues vs. control." (PMID 33846436, 2021). "We found that IL-1B regulates iNOS+ immune cell infiltration, without affecting either the accumulation of CD163+ immune cells or the growth of tumour-associated CD34+ blood vessels." (PMID 34290237, 2021). "In addition, pooled results from two studies indicated that elevated CD163+ TAMs were more prone to advanced tumor-stage with a fixed-effects model (OR: 4.11, 95% CI 2.12–7.96)." (PMID 34026635, 2021). "In BC, high levels of tumor infiltrating CD163+ macrophages have been associated with higher proliferation rates, lower tumor cell differentiation, and a lack of hormone receptor (HR) expression (HR negativity)." (PMID 33849622, 2021). "The complete tumor removal was accompanied by a significant decrease in CD163+ cell subset." (PMID 33917598, 2021). "The presence of tumor-infiltrating immune cells, characterized by the markers CD68, CD163, and CCL2, was associated with a superior prognosis, and chemotherapy may not add an advantage for prognosis." (PMID 33467469, 2021). "In HCC patients, TAMs, interacting with IL-17-producing cells, have been found to promote tumor proliferation, and CD163-positive TAMs play a suppressive role in the antitumor immune response, which may impact the recurrence of HCC." (PMID 34638613, 2021). "Pearson correlation coefficients were calculated, and the results indicated that BGN presented the strongest correlations with TIIC markers for monocytes (CD86, CD115), tumor-associated macrophages (TAMs) (IL-10, CCL2, CD68), M2 macrophages (CD163, VSIG4, and MS4A4A) and Tregs (FOXP3, CCR8, TGFβ)." (PMID 35096572, 2021). "CD68 and CD163 were occasionally positive in tumor tissues from some patients." (PMID 34458140, 2021). "To further study the potential clinical relevance of PLXDC2 expression in tumor progression, we made use of 67 TMA with adequate PLXDC2 and CD163 staining effect of GC patient samples to compare the expression of PLXDC2 between GC tumor tissues and stromal tissues." (PMID 34124056, 2021). "They found both tumor volume and volumetric growth were positively correlated with CD163 expression, and the relationship between PD-L1 and growth strengthened with increasing CD163 infiltration, suggesting a prominent role of immunotherapy in VS treatment." (PMID 34646772, 2021).
tumor (continued). "Pivotal clinical studies confirmed both the promising pre-clinical data and the prognostic relevance of both total and M2 TAM, in which CD68/CD163 double-positive M2 TAM were associated with an increased micro-vessel density and reduced survival, independently of the tumor stage." (PMID 34298810, 2021). "Considering the results regarding the tumor immune microenvironment, p14/ARF-negative tumors seem to have an immune microenvironment less sensitive to immune checkpoint inhibitors, being associated with low PD-L1 and CD4 expression, and high CD163 percentage." (PMID 33828993, 2021). "When the xCell scores were estimated, the tumor stage was significantly associated with the number of macrophages and that the number of infiltrating CD68-, CD163- and CD204-positive macrophages were significantly associated with tumor heterogeneity as evaluated by TA." (PMID 34244567, 2021). "Moreover, in the tumor core the percentage of CD163+ cells (median: 9%, mean: 12%) was significantly higher than the percentage of CD45+ cells (p = 0.006)." (PMID 34654395, 2021). "Interestingly, more M1 (CD11c(+)) macrophages infiltrated the tumor nest than in the tumor stroma, and more M2 (CD163(+)) macrophages infiltrated the tumor stroma than the tumor nest." (PMID 34407796, 2021). "Furthermore, in EBV-negative DLBCL, the CD163/CD68 ratio was higher among advanced-staged/high-tumor burden disease." (PMID 34527580, 2021). "The role of CD163 as a marker of the M2 phenotype is highly questionable due to its expression of the macrophages in mixed chronic inflammatory conditions; however, CD163 is frequently used to identify tumor-supporting TAM in various types of cancer." (PMID 35237501, 2021). "Kaplan–Meier analysis revealed a shorter Progression Free Survival in MLPS patients whose tumor tissues were highly vascularized and heavily infiltrated by CD163 positive macrophages, indicating a clear-cut link between M2-like macrophage abundance and poor prognosis in patients." (PMID 34209309, 2021). "Moreover, CD163 expression was positively correlated with most gene markers of these tumor-infiltrating immune cells in both the TCGA and CGGA cohorts, including CD8A, CD8B, STAT6, STAT5A, and PDCD1." (PMID 34395626, 2021). "CD163+ macrophage staining can be obviously seen in tumor stroma." (PMID 33765961, 2021). "CD163 is a marker of M2-like macrophages, which are related to immune escape and tumor progression." (PMID 34837690, 2021). "Hu compared high and low CD163 expression in the tumour stroma or islets with OS." (PMID 33481339, 2021). "CD14+, CD68+ and CD163+ cell densities in the intratumoral tumor (IT tumor) compartment (p = 0.001; p < 0.001 and p = 0.004, respectively) and peritumoral tumor (PT Tumor) compartment (p = 0.001; p = 0.003 and p < 0.001, respectively) differed between grades of differentiation." (PMID 34194435, 2021). "A relatively lower expression of CD47 in tumor cells or higher CD163+ TAMs was related to poor prognosis, suggesting that they might act as indicators for PanNET prognosis." (PMID 33765961, 2021). "Together, our GBM data suggest that BTK protein may be expressed in SOX2-positive tumour cells, CD163-positive macrophages, and a third population of cells which needs further characterisation." (PMID 34645618, 2021). "We hypothesized that low CD86+ and high CD163+ TAM levels were clearly correlated with aggressive tumor phenotypes." (PMID 34512652, 2021). "Taken together with tumor stage, the stromal CD86/CD163 ratio may serve as a clinically useful tool to improve the prediction of tumor recurrence and guide more appropriate therapies for different risk subgroups." (PMID 34512652, 2021). "Schematically, they can be divided into M1-macrophages with anti-tumour activity, and M2-macrophages (CD163+), which are characterized by a pro-tumour activity through the secretion of several cytokines (IL-1, IL-6, IL-10, Vascular Endothelial Growth Factor VEGF and TGF-β)." (PMID 34206956, 2021).
tumor (continued). "Considering that CD16 is indicative for the maturation of monocytes in circulation, we can hypothesize that CD163 expression is stimulated by the circulating factors produced by the tumor." (PMID 35237501, 2021). "Furthermore, in low-grade carcinomas, CD163+ TAMs were mainly located in the stroma, and the number of CD163+ TAMs in the tumor nest also increased with tumor grade." (PMID 33807310, 2021). "Kim SJ and Ham JS analyzed the serum cytokines and CD68- and CD163- positive macrophage in tumor tissue of 37 AITL patients after CHOP chemotherapy, and found that high IL-10 and M2 macrophage tissue infiltration all indicated low OS and poor response to treatment." (PMID 33154947, 2020). "Immunohistochemical scores of CD68 and CD163 were statistically related to bulky disease (p value = 0.005 for both), tumor stage (p value = 0.02 for both), International Prognostic Score (IPS) (p value = 0.04 and 0.02 respectively), and the overall response rate (ORR) (p value = 0.001)." (PMID 32372254, 2020). "The CD163+ cell count in the tumour region revealed much higher cell densities in both the stromal (CT: Median/SD 83.6/±421.5 cells/mm2; IF: 100.4/±462.9 cells/mm2) and intraepithelial compartments (CT: Median/SD 121/±172.1 cells/mm2; IF: 148.6/±208.6 cells/mm2)." (PMID 32075091, 2020). "We investigated the link between TAMs and tumor proliferation and found a strong positive association between the density of CD68+/CD163+ TAMs in the stroma and proliferation of tumor cells as determined by Ki67 staining, but no such association was detected in parenchymal or luminal areas." (PMID 32190817, 2020). "Therefore, we characterized the macrophage population by evaluating CD163 in our cohort, a marker for alternatively activated macrophages (M2) considered to promote tumor progression." (PMID 31980961, 2020). "Double immunostainings for CD68 and CD163 antigens were applied to pre-RT tissue samples from four locations: central tumour (CT), invasive front (IF), normal tissue taken from tumour proximity (prox) and normal tissue that was sampled distant from the tumour (dist)." (PMID 32075091, 2020). "However, within our dataset we were unable to directly correlate IHC and flow cytometry results for CD163 expression in individual tumours, which was in agreement with previous literature." (PMID 32070062, 2020). "It is yet unknown if CD163 has a function in disease development per se or the expression level just reflects the inflammatory state of the macrophages in the tumor." (PMID 32752088, 2020). "Indeed, within stage III tumors, higher CD68 infiltration in the intra-tumoral regions is associated with decreased overall survival, and a higher CD80/CD163 ratio at the tumor invasive front correlates with a favorable outcome." (PMID 32962159, 2020). "Interestingly, we found heterogeneous levels of r‐CD163 in SNDil‐MΦ, indicating a tumor‐dependent phenomenon." (PMID 32082570, 2020). "In addition, increased expression of CD163+ TAMs and CXCL12 in tumor stroma (TS) and invasive tumor margin (TM) is intimately associated with tumor progression in GC." (PMID 33224886, 2020). "Tumor expression of PD-L1 (CD163-PD-L1+; >25 average count) was found in patient #1, #2, #3 and #4." (PMID 32547707, 2020). "The authors hypothesized that the enrichment of “inflammatory” CD68+CD16+ macrophages over immunosuppressive CD163+ macrophages could create a more favorable TME for the anti-tumor activity of Ipilimumab." (PMID 32793228, 2020). "Moreover, CCL2 and CXCL10 was present in the tumor and the tumor microenvironment and co-localized with almost all Nestin+, Iba-1+, CD163+ or CD16+ cells, suggesting the same distribution and localization." (PMID 32943658, 2020). "Patients with activated tumor stoma showed high stromal cell infiltration (fibroblasts, endothelial cells, and monocyte macrophages), epithelial-mesenchymal transition, tumor angiogenesis and M2 macrophage polarization (CD163 and CD206)." (PMID 33122682, 2020).